PDZD9 (PDZ domain containing 9)
Synonyms: C16orf65; MGC50721
Tractability: No criterion of Open Targets' tractability assessment is met for any kind of drug.
Gene: Protein-coding gene on chromosome 16 (21,983,865 to 22,001,116, reverse strand). Ensembl gene ENSG00000155714.
Subcellular location (Human Protein Atlas): Cytosol; Plasma membrane; Nuclear speckles; Primary cilium
Genetic constraint (gnomAD): Loss-of-function variants: 13 observed, 16.64 expected, observed/expected ratio (o/e) 0.78, 90% interval 0.51 to 1.24. The upper end of that interval is the gene's LOEUF score, 1.24, which puts it in group 5 of 6, group 1 being the genes least tolerant of losing a copy. Missense variants: 288 observed, 321.11 expected, observed/expected ratio (o/e) 0.9, 90% interval 0.81 to 0.99. Synonymous variants: 120 observed, 114.85 expected, observed/expected ratio (o/e) 1.04, 90% interval 0.9 to 1.22.
Homologues: Orthologues: chimpanzee PDZD9 (100% identical), dog PDZD9 (79% identical), pig PDZD9 (77% identical), rabbit PDZD9 (76% identical), macaque PDZD9 (72% identical), guinea pig PDZD9 (71% identical), mouse Pdzd9 (68% identical), rat Pdzd9 (67% identical).
Diseases named in the same sentence as PDZD9 in open-access papers:
PDZD9 is named in the same sentence as 1 disease in open-access papers, as found by Europe PMC text mining. Sharing a sentence is not in itself a finding about the gene and the disease.
PDZD9 shares sentences with these, for which no sentence is quoted: schizophrenia (1 paper).